KCNJ11 (potassium inwardly rectifying channel subfamily J member 11)
Diseases named in the same sentence as KCNJ11 in open-access papers (continued):
Sharing a sentence is not in itself a finding about the gene and the disease.
hyperinsulinism (39 papers, 2008 to 2026). Abnormally high levels of insulin in the blood. "That is, this channel regulates insulin secretion in pancreatic beta cells; therefore, when mutations occur in the genes encoding SUR1 (ABCC8) and Kir6.2 (KCNJ11), serious problems in insulin secretion arise, leading to neonatal diabetes or hyperinsulinism." (PMID 41009376, 2025). "KCNJ11 is a subunit of the ATP-sensitive potassium channel, and mutations in this gene are associated with hyperinsulinemia." (PMID 40606662, 2025). "KATP-channel inactivating mutations in ABCC8 associated with mutations in the KCNJ11 gene cause 97% of cases of diazoxide-unresponsive hyperinsulinism." (PMID 38791571, 2024). "Recessively inherited loss-of-function mutations in either ABCC8 or KCNJ11 are the most common cause of congenital hyperinsulinism." (PMID 38366195, 2024). "Our case involved a monogenic cause of hyperinsulinism, which affects 1/50 000 live births, with the most severe forms being caused by inactivating mutations of the ABCC8 and KCNJ11 genes (that account for 36–70% of congenital hyperinsulinism cases)." (PMID 39153498, 2024). "It’s supposed that early hyperinsulinism caused by the KCNJ11 gene mutation, as well as delayed epiphyseal closure due to estrogen deficiency, contributed to the patient’s exceptionally tall stature." (PMID 38152125, 2023). "Although Kcnj11 +/− mice display hyperinsulinism, homozygous loss of the gene results only in transient hyperinsulinemia in neonates, unexpectedly followed by loss of insulin secretion and glucose intolerance in adulthood." (PMID 35008927, 2022). "Mutations in the KATP channel genes, ABCC8 and KCNJ11, are the most common cause of congenital hyperinsulinism." (PMID 34633981, 2021). "Loss-of-function mutations in SUR1 or less commonly, KCNJ11, lead to hyperinsulinism, whereas mutations in KCNJ11 that decrease ATP inhibition of KATP cause neonatal permanent neonatal diabetes." (PMID 34717951, 2021). "It was reported that the mutation of KCNJ11 R136 to other amino acids, such as Arg136His, Arg136Leu, can cause congenital hyperinsulinemia, and the authors didn’t conduct functional studies on related mutations." (PMID 34465386, 2021). "Mutations in ABCC8 and KCNJ11 are the major cause of neonatal diabetes mellitus and congenital hyperinsulinism." (PMID 32882918, 2020). "In our patient, it is likely that the persistent hyperinsulinism was due to a loss of functional K-ATP channels within the pancreatic beta cell as a result of the KCNJ11 mutation(s)." (PMID 27173951, 2016). "In these patients, the persistent hyperinsulinism results from the unmasking of a recessively inherited mutation in ABCC8 or KCNJ11 within the pancreatic tissue." (PMID 27173951, 2016). "The most frequent genetic cause of hyperinsulinism and neonatal diabetes is pathogenic mutations in KCNJ11 and ABCC8; the subunits of the β-cell ATP-sensitive potassium channel, a crucial element of the glucose-stimulated insulin secretion pathway, are encoded by these genes." (PMID 38283146, 2023). "KCNJ11 mutations that alter channel trafficking can cause hyperinsulinism, and trafficking alterations may be involved in NDM mutations." (PMID 27681078, 2016). "We now report a patient with congenital hyperinsulinism with hemihypertrophy resulting from novel paternally inherited, recessively acting KCNJ11 mutation(s), which have been unmasked by paternal uniparental isodisomy that extends from 11p15.5 to 11p15.1 within the pancreatic tissue." (PMID 27173951, 2016). "Mutations in the SUR1 (ABCC8) and the Kir6.2 (KCNJ11) cause familial hyperinsulinemia in infancy, while some polymorphisms in these genes (exon 16-3t/c and exon 18 C/T of ABCC8 and E23K of KCNJ11) have been reported to be associated with T2D in several populations at different degrees." (PMID 25309595, 2014).
hyperinsulinism (continued). "Our recommendation is to send genetic testing as soon as possible for the child and his/her parents, especially for the diazoxide-unresponsive cases as the detection of a single recessive paternal KATP mutation (ABCC8 or KCNJ11) has a positive predictive value of 94% for focal hyperinsulinism." (PMID 23384201, 2013). "The most common genetic cause of hyperinsulinism is gain-of-function variants in ABCC8 and KCNJ11, which make up the ATP-sensitive potassium channel (KATP)." (PMID 40605820, 2025). "Disease-causing single nucleotide variants affecting over 30 genes are known to cause persistent hyperinsulinism with mutations in the KATP channel genes (ABCC8 and KCNJ11) most commonly identified in children with severe persistent disease." (PMID 35872984, 2022). "Individuals with hyperinsulinism born appropriate or large for gestation and unresponsive to diazoxide treatment are most likely to have an ABCC8 or KCNJ11 mutation." (PMID 34633981, 2021). "The major treatment for congenital hyperinsulinism and neonatal diabetes patients carrying ABCC8 or KCNJ11 mutations is diazoxide (SUR1 activator)." (PMID 32882918, 2020). "The repression of Kir6.2/SUR1 channels stimulates the release of insulin, and it has been reported that mutations and deficiencies of ABCC8 and KCNJ11 induce hyperinsulinism." (PMID 32906679, 2020). "Gain-of-function mutations in the genes encoding the Kir6.2 (KCNJ11) and SUR1 (ABCC8) subunits of the channel cause neonatal diabetes, whilst loss-of-function mutations in these genes result in congenital hyperinsulinism." (PMID 28663158, 2017). "Mutations in eight different genes (ABCC8, KCNJ11, GLUD1, CGK, HADH, SLC16A1, HNF4A and UCP2) have been identified to date in patients with congenital forms of hyperinsulinism (CHI)." (PMID 23032149, 2012). "Loss-of-function mutations in either the pore-forming (inwardly rectifying potassium channel 6.2 [Kir6.2], encoded by KCNJ11) or regulatory (sulfonylurea receptor 1, encoded by ABCC8) subunits result in congenital hyperinsulinism, whereas gain-of-function mutations cause neonatal diabetes." (PMID 38366195, 2024). "LOF mutations in the ABCC8 or KCNJ11 genes lead to KATP channel dysfunction and hyperinsulinism." (PMID 38791571, 2024). "Mutations in the Kir6.2 (KCNJ11 gene, omim #600937) and SUR1 (ABCC8 gene, omim #600509) subunits lead to permanent closure of the channel and account for 40–45% of all cases of congenital hyperinsulinism." (PMID 31840185, 2020). "It is well established that the potassium inwardly rectifying channel, subfamily J, member 11 (KCNJ11) gene located at chromosome 11p15.1 is involved in insulin secretion in humans and that mutations in this KCNJ11 gene can cause congenital hyperinsulinism and permanent neonatal diabetes." (PMID 25165692, 2014). "Inactivating mutations in the genes encoding the two subunits of the ß-cell ATP-sensitive potassium channel (KATP channel), ABCC8 and KCNJ11 (encoding SUR-1 and Kir6.2, respectively), cause the most common and severe form of hyperinsulinism, although mutations in ABCC8 are more common." (PMID 23384201, 2013). "BRSK2 variant carriers may exhibit congenital hyperinsulinism due to β-cell hypersecretion, which causes a vicious cycle between hyperinsulinemia and insulin resistance, akin to the most recognized genetic variants of ABCC8 and KCNJ11 in T2DM." (PMID 37188647, 2023). "However, BWS patients usually do not carry pathogenic variants in either ABCC8 or KCNJ11 and the underlying mechanism responsible for hyperinsulinism in these patients is not known." (PMID 36339418, 2022). "Inactivation mutation in KCNJ11 gene can lead to continuous closure of KATP channel, continuous depolarization of β cell membrane, continuous inflow of extracellular Ca2+, excessive secretion and release of insulin, resulting in congenital hyperinsulinism hypoglycemia." (PMID 34465386, 2021).
hyperinsulinism (continued). "It is therefore likely that ABCC8 and KCNJ11 are co-regulated as a result of TFAP2A-mediated chromatin looping, and that the disruption of TFAP2A binding at either locus leads to congenital hyperinsulinism." (PMID 28100260, 2017).
MODY (35 papers, 2008 to 2026). "A study from the UK Biobank provides robust statistical evidence supporting the fact that mutations in HNF1A, HNF4A, GCK, and KCNJ11 are among the most common well-established forms of MODY." (PMID 40149950, 2025). "The HNF1B MODY accounts for < 5% of all MODY subtypes, while mutations in KCNJ11 MODY are very rare and found in < 1% of all MODY cases." (PMID 39420905, 2024). "Her presentation suggested a diagnosis of MODY, and genetic screening identified a dominantly inherited mutation in KCNJ11, S118L." (PMID 38366195, 2024). "Defects in the pancreatic KATP channels can lead to HH, NDM (both transient and permanent), MODY, and variants in KCNJ11 and KCNQ1 channel genes are associated with T2DM." (PMID 31137773, 2019). "Pathogenic variants were also identified in genes associated with MODY (maturity-onset diabetes of the young), including ABCC8, GCK, KCNJ11, and WFS1." (PMID 40149731, 2025). "To analyze the frequencies of the carriers of such mutations in our cohort, we analyzed genes (HNF1A, HNF4A, HNF1B, INS, ABCC8, and KCNJ11) in which a significant number of missense mutations have previously been reported in MODY, neonatal diabetes mellitus, or early onset diabetes." (PMID 29207974, 2017). "However, no previous study has ever described a family with a well-defined MODY due to a KCNJ11 mutation." (PMID 22701567, 2012). "Therefore, since the affected carriers of a KCNJ11 mutation should ideally receive oral sulfonylureas, the routine genetic diagnosis of MODY families should now include KCNJ11, even if the prevalence of KCNJ11 mutations in MODY seems quite low." (PMID 22701567, 2012). "Therefore, it is highly probable that KCNJ11 p.Glu227Lys mutation is causal for MODY in the analyzed pedigree." (PMID 22701567, 2012). "Furthermore, a mutation in the KCNJ11 gene was reported to be associated with MODY." (PMID 38675722, 2024). "Mutations in seven of these genes, including ABCC8, GCK, HNF1B, INS, KCNJ11, NEUROD1, and PDX1, are implicated in both NDM and MODY." (PMID 39859454, 2025). "Median age at diagnosis ranged from 9.9 years in GCK‐MODY (Q1–Q3: 6.2–13.1 years) and INS‐MODY (2.7–13.7 years) to 14.3 years (5.0–17.1) in individuals with KCNJ11‐MODY." (PMID 39511990, 2024). "For the CEL, PDX1, INS, KCNJ11 and ABCC8 genes, MODY is caused only by specific variants resulting in dominant‐negative/gain of function effects; null variants in these genes do not cause MODY." (PMID 35445424, 2022). "Three MODY subtypes are associated with mutations in hepatocyte nuclear factor (HNF) transcription factors, and two others are associated with mutations in ABCC8 and KCNJ11, which encode subunits of the ATP-dependent potassium channel in pancreatic beta cells." (PMID 39902162, 2024). "Mutations in KCNJ11 or ABCC8 that increase the opening probability of the channel hyperpolarise the beta cell membrane and inhibit insulin secretion, causing either neonatal diabetes or MODY." (PMID 35618782, 2022). "Therefore, the molecular diagnosis of MODY should include KCNJ11 as affected carriers can be ideally treated with oral sulfonylureas." (PMID 22701567, 2012). "Indeed, member IV1 of our French MODY family, who carries the KCNJ11 p.Glu227Lys mutation, has normal fasting plasma glucose level at 39 years (5.3 mmol/l)." (PMID 22701567, 2012). "Some MODY subtypes (e.g., ABCC8, KCNJ11, HNF1α, and HNF4α MODY) are manageable through KATP inhibition — i.e., sulfonylurea use." (PMID 34032641, 2021). "In a recent study, among 16 patients with MODY who were offered treatment switch after genetic diagnosis, nine (six HNF1A, three KCNJ11) were stably switched from insulin to oral sulfonylurea but seven (three HNF4A, two ABCC8 and one each HNF1A and KCNJ11) had to restart insulin." (PMID 35618782, 2022). "Moreover, we also detected variants in rare MODY-related genes, including NEUROD1 (MODY6), KCNJ11 (MODY13) and APPL1 (MODY14), among other MODY subtypes." (PMID 36613572, 2022).
MODY (continued). "The mechanisms underlying MODY include β cell KATP channel dysfunction (e.g., KCNJ11 [MODY13] or ABCC8 [MODY12] mutations); however, no other β cell channelopathies have been associated with MODY to date." (PMID 34032641, 2021). "GCK-MODY typically does not require drug therapy, whereas other forms of MODY, such as HNF1A, HNF4A, and KCNJ11, generally respond well to sulfonylurea therapy." (PMID 40149950, 2025).
neonatal diabetes mellitus (32 papers, 2010 to 2026). Neonatal diabetes mellitus presents as hyperglycemia, failure to thrive and, in some cases, dehydration and ketoacidosis which may be severe with coma, in a child within the first months of life. "Research has demonstrated that the most common mutation sites associated with Neonatal Diabetes Mellitus (NDM) are located within the KCNJ11 and ABCC8 genes, which encode the Kir6.2 and SUR1 subunits of the KATP channel, respectively." (PMID 40650956, 2025). "As for the Kir6.2 subunit, gain-of-function (GOF) mutations (KCNJ11/ABCC8) in the Kir6.2 subunits of pancreatic KATP channels have been identified as the most common cause of human neonatal diabetes mellitus, nDM." (PMID 39065708, 2024). "At least 30 mutations in the KCNJ11 gene have been identified in people with permanent neonatal diabetes mellitus, and mutations are also associated with gestational diabetes mellitus." (PMID 26978842, 2016). "Gain-of-function mutations in the genes that encode either subunit, ABCC8 (SUR1) or KCNJ11 (Kir6.2), lead to channel hyperactivity, which attenuates the insulin response to hyperglycemia and causes neonatal diabetes mellitus (ND)." (PMID 25926814, 2015). "It is also described that gain-of-function mutations of the KCNJ11 gene cause neonatal diabetes mellitus, and loss-of-function mutations lead to congenital hyperinsulinism." (PMID 24068186, 2013). "Recent advances in molecular genetics have shown that activating mutations in KCNJ11 (the gene that encodes for the Kir6.2 subunit of the KATP potassium channel of the pancreatic β-cell) is a common cause of permanent neonatal diabetes mellitus." (PMID 20220270, 2010). "Mutations in KCNJ11 can also cause neonatal diabetes mellitus (NDM), which occurs mainly in the first 6 months of age and rarely between 6 months and 1 year of age." (PMID 38095268, 2024). "Six patients of Group 2 carried a pathogenic or likely pathogenic variant in KCNJ11 (3 variants), ABCC8 (1 variant) and PDX1 (biallelic variants); a patient with transient neonatal diabetes mellitus had 6q24 methylation defects (Online resource 1, left panel)." (PMID 36178555, 2023). "Heterozygous gain of function mutations in KCNJ11 can cause neonatal diabetes mellitus (NDM)." (PMID 34732776, 2021). "The most frequent genetic causes of neonatal diabetes mellitus with abnormal β cell function are abnormalities of the 6q24 locus and mutations of the ABCC8 or KCNJ11 genes coding for the potassium channel in the pancreatic β cell." (PMID 33102403, 2020). "Insulin secretion in sulfonylurea-treated KCNJ11 permanent neonatal diabetes mellitus (PNDM) is thought to be mediated predominantly through amplifying non-KATP-channel pathways such as incretins." (PMID 31908791, 2019). "Nucleotide variations in genes encoding KATP channel proteins, such as potassium channel inwardly rectifying subfamily J member 11 (KCNJ11) and ATP-binding cassette, subfamily C, member 8 (ABCC8), are associated with the onset of neonatal diabetes mellitus." (PMID 26161088, 2015). "Mutations in genes encoding KATP channel proteins—KCNJ11 (encoding Kir6.2) and ABCC8 (encoding SUR1)—lead to neonatal diabetes mellitus." (PMID 24324494, 2013). "Interestingly, SNPs in ABCC8 and KCNJ11 were reported in patients with neonatal diabetes mellitus and DCD." (PMID 38137073, 2023). "Similarly, variants in KCNJ11, ABCC8 and INS accounted for 50% of neonatal diabetes mellitus (NDM) cases and were sequenced by Sanger first in some studies." (PMID 37794142, 2023). "Extracellular Ca2+ can’t inflow and insulin can’t be secreted normally, which leads to a series of continuous and varying degrees of glucose metabolism abnormalities, including neonatal diabetes mellitus, impaired fasting glucose, impaired glucose tolerance and KCNJ11-MODY." (PMID 34465386, 2021).
neonatal diabetes mellitus (continued). "We propose mechanistically that low-dose SUs do not cause hypoglycemia due to their effect on the KATP channel open state, similar to their mechanism observed in KCNJ11 neonatal diabetes mellitus (NDM)." (PMID 38267622, 2024). "For example, among the 19 diseases with ‘Ketosis’ as clinical sign, two of them were classified as oligogenic: maple syrup urine disease with 3 genes (BCKDHA, BCKDHB and DBT) and Permanent neonatal diabetes mellitus with 4 genes (GCK, INS, KCNJ11 and ABCC8)." (PMID 28715999, 2017). "Accurate molecular diagnosis of monogenic non-autoimmune neonatal diabetes mellitus (NDM) is critical for patient care, as patients carrying a mutation in KCNJ11 or ABCC8 can be treated by oral sulfonylurea drugs instead of insulin therapy." (PMID 21049026, 2010).
Hypoglycemia (31 papers, 2008 to 2026). A decreased concentration of glucose in the blood. "We report two cases of persistent neonatal hypoglycemia associated with mutations in the KCNJ11 and ABCC8 genes, encoding the Kir6.2 and SUR1 subunits of the adenosine triphosphate-sensitive potassium channel." (PMID 41869142, 2026). "In turn, Genetic variants in ABCC8 (SUR1) and KCNJ11 (Kir6.2) affect the function of ATP-sensitive potassium channels, modulating drug efficacy and the risk of hypoglycemia." (PMID 40395625, 2025). "Studies in patients with NDM due to activating mutations in KCNJ11 found that these patients were able to effectively switch from insulin to high-dose SU, with resulting tight glycemic control while avoiding hypoglycemia." (PMID 38267622, 2024). "Sixteen family members carried the ABCC8 or KCNJ11 mutations; only two had hypoglycemia detected at birth and four others reported symptoms of hypoglycemia." (PMID 31464105, 2019). "The patient and the other family members who exhibited hypoglycemia are all heterozygous for the KCNJ11 (C83T) mutation, suggesting that A28V hKir6.2 is a dominant-negative mutation that can suppress normal KATP channel trafficking." (PMID 29087246, 2017). "Dominant inactivating ABCC8 and KCNJ11 mutations are less frequent, but are usually associated with a milder form of hypoglycaemia that is responsive to diazoxide therapy." (PMID 20573158, 2011). "All patients with the p.R301C mutation in the KCNJ11 gene have been reported to exhibit CHI and hypoglycemia." (PMID 38152125, 2023). "Three other studies investigated association between two strongly linked non-synonymous polymorphisms, S1369A (rs757110) and E23K (rs5219), in the ABCC8 and KCNJ11 genes, respectively with hypoglycemia." (PMID 34194474, 2021). "The hypoglycemia screen in the neonatal period showed an inappropriate insulin level at the time of hypoglycemia, thus confirming CHI, and genetic analysis showed a homozygous KCNJ11 pathogenic variant." (PMID 40492016, 2025). "For example, mice generated with a deletion of ABCC8 or KCNJ11, or the homozygous recessive KCNJ11 mutation p.(Tyr12Ter), do not have the sustained neonatal hypoglycemia observed in humans with homozygous null mutations." (PMID 32027066, 2020). "Loss-of-function pathogenic variants in KCNJ11 (the gene that encodes Kir6.2) can lead to congenital hyperinsulinism (CHI), a disorder characterized by persistent β-cell depolarization which results in excessive insulin secretion even in the presence of severe hypoglycemia." (PMID 37408765, 2023). "This gene is responsible for the clinical form of hypoglycemia associated with high levels of serum ammonia, and is also the major gene affected in cases in which no mutations are detected in genes ABCC8 and KCNJ11." (PMID 25972930, 2015).